Y_RNA (Y RNA )
Gene: Miscellaneous RNA gene on chromosome 6 (29,750,371 to 29,750,472, forward strand). Ensembl gene ENSG00000199290.
Homologues: Orthologues: guinea pig Y_RNA (93% identical). Paralogues in human: RNY3 (93% identical), Y_RNA (92% identical), RNY3P1 (91% identical), Y_RNA (91% identical), RNY3P14 (90% identical), Y_RNA (90% identical), Y_RNA (89% identical), Y_RNA (88% identical), RNY3P11 (87% identical), Y_RNA (87% identical), RNY3P16 (86% identical), Y_RNA (86% identical), and 96 more.